IL17A (interleukin 17A)
Diseases named in the same sentence as IL17A in open-access papers (continued):
Sharing a sentence is not in itself a finding about the gene and the disease.
cancer (continued). "Consequently, IL-17A induces synthesis of various gene products, including pro-inflammatory cytokines, chemokines, matrix metalloproteinases and growth factors, to mediate diverse biological functions in autoimmunity, inflammation, host defense, and cancer." (PMID 28562353, 2017). "They demonstrated that IL-17A and possibly IL-17F could initiate transduction pathways, increase expression of MAPKs and recruit neutrophils participation in gastric inflammation and thus promote cancer progression through IL-17R docking." (PMID 27589729, 2016). "Undoubtedly, therefore, involvement of certain interleukins including IL-6, IL-4, IL-17A and IL-32β in certain EMT pathways signifies their specific contribution to metastatic processes, thereby warranting further work into the development of diagnostic and immunotherapeutic tools in cancer." (PMID 25590298, 2015). "IL-17A is mainly secreted by Th17 cells, which may influence cancer progression." (PMID 25181290, 2014). "However, the role of IL-17A in cancer was inconsistent according to previous reports." (PMID 24905806, 2014). "It remains controversial whether IL-17A promotes or inhibits cancer progression." (PMID 23372655, 2013). "Consequently, depending on the effector or regulatory role of dendritic cells, blocking IL-17A, may be either dangerous or beneficial for cancer outcomes, thus contributing to the apparent controversy around the role of IL-17A in cancer." (PMID 23441221, 2013). "Consequently, even with the use of knockout mice, it remains controversial whether IL-17A promotes or inhibits cancer progression." (PMID 23372655, 2013). "Recent advances in the pathogenesis of CD and the discovery that the inflamed gut of CD patients contains high levels of Th17-type cytokines (e.g., IL-17A, IL-21, IL-22), which are mitogenic for epithelial cancer cells, could explain this apparent contradiction." (PMID 23109839, 2012). "Regarding the involvement of IL-17A in the development of radiation-induced pulmonary injury (RIPI), both in animal models and in patients with cancer undergoing RT, has been preliminarily studied and provided supportive evidence." (PMID 41229527, 2025). "The immunohistochemical analysis revealed significantly higher expression of CD44, MYC, IL17A, CXCL1, FCGR3A, SPP1, and IL1A in cancer tissues, while CXCL12 and CCL5 showed significantly higher expression in adjacent normal tissues." (PMID 39767563, 2024). "Interleukin 17A (IL-17A), the major cytokine secreted by Th17, is known to promote CRC progression via both immune and cancer modulation mechanisms." (PMID 38177537, 2024). "Concerning interleukin correlations in healthy and cancer patients, we observed a statistically significant interdependence between IL8 and IL17A (p = 0.001) in the two groups, one strongly influencing the other’s response." (PMID 38398137, 2024). "IL-17C, another member of IL-17 family synthesized by epithelial cells, initiates an autocrine loop within epithelial tissues, which consequently upregulates IL-17A expression in TH17 cells and promotes cancer cell proliferation." (PMID 38255960, 2024). "The relationship between IL2 and IL15 has been demonstrated, including cancer therapy, as well as the relationship between IL2 and IL17A, and between IL15 and IL17A." (PMID 37691946, 2023). "Considering contradictory results observed in other research regarding the pro- and anti-cancer nature of the Th-17 cell, an individualized adjustment may be required with different cell lines and even in various stages of cancer to tackle or target the IL-17A downstream signaling axis." (PMID 36993955, 2023). "We found that IL-17A promoted NSCLC progression and inhibited autophagy through the ROS/Nrf2/p62 pathway leading to increased PD-L1 expression in cancer cells." (PMID 37978543, 2023).
cancer (continued). "As such, modulation of PD-1 and TIM-3 in cancer patients and the impact of inhibiting these molecules on γδ T cells is a point for consideration, as these immunotherapy drugs may deleteriously increase IL-17A expression and immunosuppressive neutrophil activation." (PMID 36480166, 2023). "Together, these data demonstrate how lung IL-17A–producing γδ T cell subsets are differentially controlled by PD-1 and TIM-3 in steady-state and cancer." (PMID 36480166, 2023). "IL-17A has been shown to stimulate the secretion of angiogenic CXC chemokines, including CXCL1, in live cancer cells, leading to faster growth of implanted syngeneic tumors." (PMID 37686343, 2023). "IL-17A levels are elevated in the stroma and intestinal epithelium of CRC in patients with colorectal adenoma throughout all stages of cancer." (PMID 36358736, 2022). "These two IL-17A promoter SNPs can possibly be utilized as potential biomarkers in the absence of an MT EGFR in LUAD patients who smoke, as well as a cancer aggressiveness predictor for WT EGFR LUAD patients." (PMID 33802737, 2021). "Many inflammatory factors such as interleukin-1beta (IL1b), interleukin-17a (IL17a) and interleukin-6 (IL6) have been reported to facilitate HCC progression by promoting proliferation, metastasis and cancer stem cells (CSCs) formation." (PMID 33661757, 2021). "CAF-derived soluble factors including IL6, IL17A, IGF1, IGF2, and nitric oxide indirectly can mediate the development of cancer treatment resistance." (PMID 32932015, 2021). "Functionally, FoxP3+IL17A+ Tregs from sporadic CRC patients maintained their suppressive phenotype against CD4+ and CD8+ T cells but they were involved in cancer initiation by targeting epithelial cells in an IL17A-dependent manner." (PMID 32937953, 2020). "DAMPs not only prime cancer-killing CD8+ T cells for the secretion of interferon γ (IFNγ), but also anti-cancer CD4+ T cells for the secretion of IFNγ and IL-17A." (PMID 31739582, 2019). "While the Foxp3-inducing effect of the cancer ascites was mimicked by the addition of recombinant TGF-β, the ascites and TGF-β differed in that TGF-β alone induced IL-17A together with Foxp3 expression." (PMID 31310618, 2019). "Our findings demonstrate, for the first time, that dual targeting of inflammatory (IL-17A) and extracellular matrix remodeling (MMP) pathways can potentially be used as a novel therapeutic approach against cancer." (PMID 29983876, 2018). "We also measured IL-17A TIL responses in this study, although the role of this pro-inflammatory cytokine in cancer has been controversial." (PMID 29731959, 2018). "In addition, the involvement of certain interleukins including IL-6, IL-4, IL-17A and IL-32β in some EMT pathways signifies their specific contribution in metastastic processes, thereby warranting further work into the development of diagnostic and immunotherapeutic tools in cancer." (PMID 25590298, 2015). "In our previous studies, DEB-TACE had a positive antitumor performance in patients with malignant tumors, with changes in the microenvironment including increased natural killer cells and CD4+/CD8+ ratios, and decreased levels of T regulatory cells and interleukin-17A." (PMID 40771818, 2025). "Notably, the presence of both pro-inflammatory (e.g., IL17A) and homeostatic (e.g., CXCL12) factors underscores the complex interplay between chronic inflammation and cancer progression in the intestinal microenvironment." (PMID 39767563, 2024). "IL-17A plays a significant role in PDAC by assisting in the early stages of cancer development, controlling the characteristics of PDAC cancer stem cells (CSCs), advancing tumor growth, and causing resistance to checkpoint inhibitors through the formation of NETs." (PMID 38835055, 2024). "In cancer patients, there is a weak quadratic correlation between the two interleukins, suggesting that IL8 may have a complex effect on interleukin 17A production." (PMID 38398137, 2024).
cancer (continued). "Cancer-bearing rats showed an enhanced expression of IL-17A in the spinal astrocytes but not in microglia and neurons." (PMID 38730655, 2024). "Interestingly, IL-17A, which is produced during inflammation, promotes cancer metastasis by inducing EMT in cancer cells via MMP7." (PMID 37555952, 2023). "In non-cancer conditions, IL-17A levels do not vary in workers exposed to pesticides, but in vitro and in vivo studies show that IL-17-A is related to cancer mechanisms." (PMID 37942322, 2023). "Furthermore, concentrations of IL-17A, IL-17F, and TNF-α have been reported to be significantly higher in saliva of patients with cancer of the oral cavity and oropharynx and are strongly associated with disease advancement." (PMID 37373022, 2023). "These cells produce high levels of IL-17A and/or IFN-γ and play role in cancer and HIV infection." (PMID 36836673, 2023). "Although Th17-associated cytokine genes (IL17A and IL17F) were not affected, we still observed that Th17 cells showed significantly decreased abundance at the late stage of cancer progression, which is inconsistent with previous findings." (PMID 36352434, 2022). "Despite reports that increased serum IL-17A represents a poor prognostic marker in AML, our findings may suggest an immuno-protective role of IL-17A in some cases, as described in other cancer types." (PMID 34842843, 2021). "Although the function of the cytokines such as IL-17A has been extensively studied in various types of cancer, nonmelanoma skin cancer (NMSC) has not received much attention." (PMID 34239554, 2021). "Additionally, by stimulating cancer cells to release inflammatory chemokines (CCL2 or CCL20), IL-17A-producing cells can enhance CD1a+ DC infiltration of the TME, which is correlated with favorable OS of patients with ESCC." (PMID 33995371, 2021). "Our results suggest that IL-17A, IL-17F, and TNF-α measured in the saliva may be a potential biomarker for cancer of the oral cavity and oropharynx." (PMID 32855976, 2020). "The mechanisms regulating CXCR3 expression, particularly expression induced by IL-17A, on CD8+ T cells in cancer remain largely unknown." (PMID 32503584, 2020). "The CyTOF analysis revealed the emergence of CD11b+/Gr-1+/CD44+ or CD11b+/Gr-1+/IL-17A+ myeloid-derived suppressor cells (MDSCs) and the absence of B220+ or CD62L+ B-cells, the CD62L+/CD4+ and CD62L+/CD8+ T-cells in the spleen of advanced cancer." (PMID 31881770, 2019). "Likewise, we found that the number of IL-17A-positive cells was significantly increased in CIN and cancer tissues compared to normal cervical tissues." (PMID 31281798, 2019). "Generation of non-IgG protein blockers of IL-17A-mediated signaling is, therefore, a valuable alternative in anti-cancer drug development." (PMID 30304852, 2018). "Despite the positive correlation between IL-17A and TSCC, the exact role of IL-17A in progression of cancer remains unclear." (PMID 28035060, 2017). "Importantly, pharmacological suppression of IL-17A signaling impaired self-renewal and tumor growth and thus demonstrated that aberrant TME signaling induced by conventional cancer therapy plays an important role in influencing the acquisition of CSC." (PMID 26742077, 2016). "While IL-17A plays important roles in cancer development, the function of IL-17F in tumorigenesis has not yet been elucidated." (PMID 22509371, 2012). "Third, in vitro studies demonstrated that IL-17A and duodenal ILC3s induce DUOX2/DUOXA2 expression, with the former specifically upregulating Duox2 protein, thereby driving mitochondrial-independent ROS production and DNA damage, a key mechanism in cancer progression." (PMID 40280932, 2025). "However, due to the presence of malignant tumors in our patient, treatment with IL-17A inhibitors and IL-36 receptor inhibitors was not considered in this case." (PMID 39281279, 2024).
cancer (continued). "Moreover, we did not observe any significant expression of IL-17A in terms of sample types, cancer stages, patient age, patient race, and gender." (PMID 38816694, 2024). "However, the pathophysiological role of IL-17A in NSCLC remains unclear, although some studies suggested its involvement in cancer cell invasion and metastasis." (PMID 37444399, 2023). "Further, it was determined that anti-IL-17A could enhance the efficacy of anti-VEGF treatments in cancer cells that did not respond to anti-VEGF treatments." (PMID 36675261, 2023). "With respect to the immune system, RFX1 acts as an activator of MHC Class II genes and represses MCP1, CD11a, CD70, IL17A, TLR4, and the TGFβ2 expressions, which could be instrumental in understanding etiology and materializing treatment strategies for cancer and other immune-related disorders." (PMID 33964962, 2021). "The role of IL-17A in cancer has not been fully elucidated, and data are controversial." (PMID 33244315, 2020). "It was proved that IL‐17A could promote migration and invasion of several kinds of cancer, but there was no published report on role of IL‐17A in migration and invasion of GBM cells." (PMID 30353649, 2019). "Therefore, we cannot reject the null hypothesis that there is no linear correlation between IL8 and IL17A in cancer patients." (PMID 38398137, 2024). "Additionally, detection of the IL‐17A+ cell percentage in clinical samples also supported the hypothesis that IL‐17A plays a pro‐metastatic role in HCC, consistent with the effects on diverse cancer types." (PMID 29689643, 2018). "Indeed, as the affinity of the N-TIMP2 and V3 domains of the heterodimer to their targets (MMP-9 and IL-17A, respectively) was not compromised, we attribute the improved ability of the heterodimer to inhibit cancer cell invasion to its ability to simultaneously bind both targets." (PMID 29983876, 2018). "IL-17A did not increase CXCR4 (68.19% vs. 64.54%) and ABCG2 (1.96% vs. 1.52%) expression in human L3.6pl cancer cells assessed by flow cytometry." (PMID 32210079, 2020). "Several studies demonstrated a cross-talk between IL-17A and MMP-9, making these two proteins ideal for dual-inhibition, non-antibody cancer therapy." (PMID 29983876, 2018). "Interestingly, a recent study showed that deficiency of IL-17A but not RORγt is associated with decreased spontaneous intestinal tumorigenesis in the APCMIN/+ mouse model, suggesting that IL-17A and RORγt may play distinct roles in cancers." (PMID 28123897, 2016). "Although inhibiting the IL-17A/STAT3 pathway may allow control of tissue fibrosis, molecular targeting drugs for IL-17A, such as secukinumab and iexkizumab, are expensive and have not been used for malignant tumors." (PMID 32488650, 2021). "Another argument in favor of a protumor impact of IL-17A and -E was the detection of an enhanced generation of low molecular weight forms of cyclin E (LMWE) in the four different cell lines (MCF7, T47D, MCF10A and IJG-1731), which has been described as a negative factor in cancer." (PMID 27589729, 2016). "Concomitant expressions of IL-17A, with or without IFN-γ, pro-angiogenic VEGF, pro-survival BCL2A1 and suppressive IL-10 or free radical peroxynitrite may indicate that IL-17A strongly supports cancer development." (PMID 23441221, 2013).
inflammation (257 papers, 2009 to 2026). Aberrant reaction of the microcirculation characterized by movement of fluid and leukocytes from the blood into extravascular tissues. "SFB mono-colonization of germ-free TnfΔARE mice confirmed the causal link and resulted in severe ileo-colonic inflammation, characterized by elevated tissue levels of Tnf and Il-17A, neutrophil infiltration and loss of Paneth and goblet cell function." (PMID 37004103, 2023). "Cigarette smoking, causing airway inflammation, is considered to be associated with neutrophil, macrophage, and activated T lymphocyte infiltration and increased cytokine concentrations, such as IL-17A and TNF-α." (PMID 36139155, 2022). "IL-17A overexpression exacerbated synovial inflammation and bone loss in the collagen-induced arthritis (CIA) model." (PMID 31485194, 2019). "This indicates pathological effects of IL-17A as well as of IL-22 that have been also implicated in other situations such as progressive airway inflammation in a murine model of bleomycin-induced airway inflammation." (PMID 28222146, 2017). "Although both LL-37 and IL-17A/F are enhanced in the lungs during neutrophilic airway inflammation, the impact of the interplay of these molecules remains unresolved." (PMID 40410820, 2025). "Consistent with qRT‐PCR results of gene expression, enzyme‐linked immunosorbent assay (ELISA) results also showed that B‐PM treatment decreased the levels of cytokines (IL‐4, IL‐6, and IL‐17A) in BALF of mice with airway inflammation." (PMID 39950864, 2025). "After transplanting respiratory microbiota from mice infected with chronic pneumonia into germ-free mice, lung inflammation increased the secretion of interleukin-17A (IL-17A) in germ free mice." (PMID 40718812, 2025). "Hyperoxia significantly alters the microenvironment at the inflammation site, which promotes the polarization of Th17 and the secretion of cytokines such as IL-17A, which increase lung inflammation by recruiting neutrophils to the inflammation site." (PMID 37485534, 2023). "Chronic neonatal lung LPS exposure induces pulmonary inflammation, increases pro-inflammatory cytokine expression, including IL-17a expression, and results in hypoalveolarization." (PMID 37744375, 2023). "In summary, we have provided a detailed in vivo analysis of IL-17a-driven pulmonary inflammation and impaired alveolar development after neonatal LPS exposure." (PMID 37744375, 2023). "Mice with airway epithelial cell-specific deletion of Sirt6 are protected against allergen-induced airway inflammation and remodeling via inhibiting IL-17A-mediated inflammatory chemokines and mesenchymal reprogramming." (PMID 38135684, 2023). "Using a murine model of airway inflammation, we demonstrated enhancement of IL-17A/F, TNF-α, LCN-2 and neutrophil chemokine KC in the lungs, thus corroborating our findings in-vivo." (PMID 36517803, 2022). "During airway inflammation, the release of IL-17A also appears to trigger the accumulation of neutrophils in the lung." (PMID 36139450, 2022). "In the functional study, exogenous RBP4 attenuated the severity of IL-17A-induced neutrophilic airway inflammation." (PMID 35095906, 2021). "IL-17A plays an important role in host defense against microorganisms and in the development of chronic inflammation." (PMID 34614111, 2021). "Adenoviral IL-17A injection in the knee joint of type II collagen-immunized mice accelerated the onset and aggravated the synovial inflammation at the site." (PMID 31485194, 2019). "Our in vivo data suggest that MCP-1 is a key target of IL-17A-mediated renal inflammation, as demonstrated by the significant upregulation at gene levels in IL-17A infused mice and by the inhibitory effect of IL-17A blockade in AngII-infused mice." (PMID 31572188, 2019). "In this study, we demonstrate that sub-acute exposure to ozone induces a production of IL-17A and neutrophilic airway inflammation, which is mediated by a mechanism involving caspase-1-IL-1 cascade." (PMID 26739627, 2016).